ERN1 (endoplasmic reticulum to nucleus signaling 1)
Description:
Serine/threonine-protein kinase and endoribonuclease that acts as a key sensor for the endoplasmic reticulum unfolded protein response (UPR). In unstressed cells, the endoplasmic reticulum luminal domain is maintained in its inactive monomeric state by binding to the endoplasmic reticulum chaperone HSPA5/BiP. Accumulation of misfolded proteins in the endoplasmic reticulum causes release of HSPA5/BiP, allowing the luminal domain to homodimerize, promoting autophosphorylation of the kinase domain and subsequent activation of the endoribonuclease activity. The endoribonuclease activity is specific for XBP1 mRNA and excises 26 nucleotides from XBP1 mRNA. The resulting spliced transcript of XBP1 encodes a transcriptional activator protein that up-regulates expression of UPR target genes. Acts as an upstream signal for ER stress-induced GORASP2-mediated unconventional (ER/Golgi-independent) trafficking of CFTR to cell membrane by modulating the expression and localization of SEC16A.
Synonyms: hIRE1p; IRE1a; IRE1; IRE1P
Tractability: Small molecule: a structure with a bound ligand is known; a high-quality ligand is known; it has a binding pocket of medium quality; it belongs to a druggable protein family. Antibody: UniProt predicts a signal peptide or a membrane-spanning region. PROTAC: it is named in the literature on targeted protein degradation; ubiquitination databases record sites on it; a small molecule that binds it is known.
Target class: Enzyme
Chemical probes: AMG-18 (high quality), PD134687, PD134689, PD134691, PD134693, PD134695, PD134697, PD134699
Gene: Protein-coding gene on chromosome 17 (64,039,080 to 64,130,819, reverse strand). Ensembl gene ENSG00000178607.
Subcellular location: Endoplasmic reticulum membrane
Pathways (Reactome):
Cellular responses to stimuli: IRE1alpha activates chaperones
Gene Ontology:
Molecular function: ADP binding; ATP binding; enzyme binding; Hsp70 protein binding; Hsp90 protein binding; identical protein binding; magnesium ion binding; platelet-derived growth factor receptor binding; protein binding; protein homodimerization activity; protein serine kinase activity; protein serine/threonine kinase activity; RNA endonuclease activity; endonuclease activity; protein kinase activity; RNA nuclease activity
Biological process: cellular response to glucose stimulus; cellular response to unfolded protein; cellular response to vascular endothelial growth factor stimulus; endoplasmic reticulum unfolded protein response; endothelial cell proliferation; insulin metabolic process; IRE1-mediated unfolded protein response; mRNA splicing, via endonucleolytic cleavage and ligation; positive regulation of endoplasmic reticulum unfolded protein response; positive regulation of JNK cascade; positive regulation of RNA splicing; positive regulation of vascular associated smooth muscle cell proliferation; protein phosphorylation; response to endoplasmic reticulum stress; intrinsic apoptotic signaling pathway in response to endoplasmic reticulum stress; mRNA catabolic process; regulation of macroautophagy; cellular response to hydrogen peroxide; mRNA processing; RNA catabolic process
Cellular component: cytoplasm; endoplasmic reticulum; endoplasmic reticulum membrane; IRE1-RACK1-PP2A complex; IRE1-TRAF2-ASK1 complex; Ire1 complex; AIP1-IRE1 complex; mitochondrion; nuclear inner membrane; protein-containing complex
Genetic constraint (gnomAD): Loss-of-function variants: 33 observed, 88.54 expected, observed/expected ratio (o/e) 0.37, 90% interval 0.28 to 0.5. The upper end of that interval is the gene's LOEUF score, 0.5, which puts it in group 2 of 6, group 1 being the genes least tolerant of losing a copy. Missense variants: 877 observed, 1,146 expected, observed/expected ratio (o/e) 0.77, 90% interval 0.72 to 0.81. Synonymous variants: 470 observed, 468.01 expected, observed/expected ratio (o/e) 1, 90% interval 0.93 to 1.08.
Homologues: Orthologues: chimpanzee ERN1 (99% identical), macaque ERN1 (99% identical), dog ERN1 (95% identical), guinea pig ERN1 (94% identical), pig ERN1 (94% identical), rat Ern1 (93% identical), mouse Ern1 (93% identical), tropical clawed frog ern1 (75% identical). Paralogues in human: ERN2 (49% identical).
Diseases named in the same sentence as ERN1 in open-access papers:
ERN1 is named in the same sentence as 345 diseases in open-access papers, as found by Europe PMC text mining. Sharing a sentence is not in itself a finding about the gene and the disease. The quoted sentences say what the papers report.
breast cancer (96 papers, 2012 to 2026). A primary or metastatic malignant neoplasm involving the breast. "Heat shock protein (HSP) 47 interacts with NM IIA via the unfolded protein response transducer IRE1α (encoded by the endoplasmic reticulum to nucleus signaling 1 (ERN1) gene) to enhance the metastatic potential of breast cancer cells." (PMID 39273383, 2024). "The conditional logistic regression adjusted for smoking habits confirmed the association between the rs196929 in ERN1 and skin (OR = 2.07, 95% C.I. 1.27–3.37, p = 0.003) and breast cancer (OR = 1.83, 95% C.I. 1.13–2.99, p = 0.013)." (PMID 36167768, 2022). "In conclusion, our results suggest that the genetic variant in ERN1 (rs196929) is associated with increased risk of skin and breast cancers." (PMID 36167768, 2022). "When the false discovery rate was applied to adjust for multiple comparisons, only skin and breast cancer remained significantly associated with ERN1." (PMID 36167768, 2022). "In summary, we demonstrated that ERN1 genetic variation is associated with skin and breast cancer and potentially associated with male’s reproductive system cancers in a population that had tooth loss." (PMID 36167768, 2022). "The association between both skin and breast cancer and ERN1 genetic variation remained significant in both analyses and the remaining results were also not remarkably different." (PMID 36167768, 2022). "Our results show a significant association between both skin and breast cancers and the rs196929 ERN1 marker in the logistic regression and the conditional logistic regression." (PMID 36167768, 2022). "When we stratified the analysis for each cancer type, our results show that the rs196929 ERN1 variant is associated with skin cancer (OR = 2.07, 95% C.I. 1.27–3.37, p = 0.003) and breast cancer (OR = 1.83, 95% C.I. 1.13–2.99, p = 0.013) in the subset of patients that had tooth loss." (PMID 36167768, 2022). "Additionally, our results stratified by cancer type showed a statistically significant association between the rs196929 in ERN1 and skin and breast cancers in both the logistic regression and the conditional logistic regression." (PMID 36167768, 2022). "The authors demonstrated that K252a (40 nM) inhibits ERN1 activity and that a dose of 1 μM reduces the colony forming ability of various breast cancer cell lines by 20–50%." (PMID 36139553, 2022). "In vivo, ERN1- or ALPK1-deficient breast cancer cells were found to be less tumorigenic than those without these deficiencies." (PMID 36139553, 2022). "Finally, we identify a chemical kinase inhibitor capable of mimicking the effect of knocking down ERN1 in several breast cancer cell lines." (PMID 27829216, 2016). "Finally, treatment with K252a, a kinase inhibitor active on ERN1, similarly impairs anchorage-independent growth of multiple breast cancer cell lines." (PMID 27829216, 2016). "In breast cancer, MYC was shown to directly regulate the transcription of ERN1 by binding to its promoter and enhancer and to cooperate with XBP1, leading to enhanced transcriptional activity." (PMID 35349489, 2022). "We show that inhibition of ERN1 and ALPK1 restricts anchorage-independent spheroid formation of an additional TNBC cell line and two luminal breast cancer cell lines." (PMID 27829216, 2016). "Breast cancer cell lines MDA-MB-453 (triple-negative) and SKBR3 (luminal) exhibited a reduced colony formation when transfected with siRNA targeting ERN1." (PMID 27829216, 2016). "The relevance of ERN1 and ALPK1 as potential therapeutic targets was reinforced by an effect of the respective siRNAs on colony formation of other breast cancer cell lines." (PMID 27829216, 2016).
diabetes (69 papers, 2012 to 2025). "In humans, pharmacological modulation of the ERN1 protein can counteract metaflammation (ubiquitous low levels of inflammation throughout the body) a process that is associated with blood vessel–affecting diseases such as atherosclerosis, chronic heart disease, and diabetes mellitus." (PMID 36175824, 2022). "Another important driver of RNA splicing enrichment directly relevant to diabetes, ERN1 (IRE1α), is also connected to ER stress." (PMID 41465472, 2025). "There are no reported cases of diabetes due to pathogenic variants in the IRE1 (ERN1) gene; however, IRE1α knockdown in C57BL/6 mice induces diabetes via a mechanism that is independent of autoimmune-mediated β-cell death." (PMID 36613674, 2022). "We observed that ATF6, CHOP, ERN1, HSPA5, and ATF4 mRNA levels were significantly increased in tissues from subjects with diabetes, and this was supported by an increased expression of ATF6 and CHOP protein expression when compared with tissue from subjects without diabetes." (PMID 33028031, 2020).
Obesity (65 papers, 2013 to 2025). Accumulation of substantial excess body fat. "Thus, upon high fat diet, deletion of Ern1 leads to increased white adipose tissue browning and improved metabolic phenotype, while Ckb knockout mice display increased predisposition to obesity and disrupted glucose homeostasis (due to impaired thermogenesis)." (PMID 39675471, 2024). "Consistent with our work, Ern1 regulating M2 macrophage polarization was also reported before, in which Ern1 affected M2 polarization in a cell-autonomous fashion to reduce proinflammatory cytokines in obesity." (PMID 32272965, 2020).
melanoma (58 papers, 2009 to 2025). A malignant, usually aggressive tumor composed of atypical, neoplastic melanocytes. "To ascertain the physiological relevance of these findings, we next assessed the survival of Ern1- and Xbp1-CKO mice implanted with B16.F10 melanoma cells." (PMID 32520957, 2020).
multiple myeloma (55 papers, 2009 to 2025). "The effect of ERN-1 upregulation and enhanced XBP1 splicing has also been observed in proteasome inhibitor treated multiple myeloma cells, ultimately contributing to cell death in this context." (PMID 36194587, 2022).
Insulin resistance (53 papers, 2010 to 2025). Increased resistance towards insulin, that is, diminished effectiveness of insulin in reducing blood glucose levels. "Examination of the KEGG pathway for NAFLD (hsa04932) demonstrated transcriptional dysregulation of mediators of insulin resistance (IRS2, P1K3R1, AKT1), steatohepatitis ( JUN, ERN1) and neutrophil infiltration and inflammation (CXCL8)." (PMID 29786565, 2018).
glioblastoma (40 papers, 2015 to 2026). The most malignant astrocytic tumor (WHO grade IV). "Oxygen deprivation upregulates PHGDH expression in glioblastoma, while ERN1 knockdown enhances this hypoxic induction by releasing repression." (PMID 41486146, 2026). "The ER stress sensor ERN1 (IRE1α) fine-tuning this circuity in glioblastoma." (PMID 41486146, 2026). "Glutamine deprivation is linked to the expression of the Endoplasmic Reticulum to Nucleus Signalling 1/Inositol Requiring Enzyme 1 (ERN1/IRE1) in the context of glioblastoma, a gene coding for a protein that acts as a detector for unfolded proteins in the endoplasmic reticulum." (PMID 39595047, 2024). "To further validate the contribution of these pathways to 12ADT-mediated cytotoxicity, we designed CRISPR guides against three target genes (ERN1, IGFBP3, IGFBP5) and transfected them separately into U251 glioblastoma cells." (PMID 32433555, 2020).
viral infection (36 papers, 2005 to 2025). "Genes in this signature code for proteins that are viral infection restricting factors (e.g. Ifitm1, Ifitm3, Gbp7), that protect against cellular or environmental stress (e.g. Abcb1a, Car2, Ern1, Serpina3g) or that regulate immune activation processes (e.g. Fgl2, Anxa1, Havcr2)." (PMID 27883012, 2016). "ERN1 (IRE1), an endoplasmic reticulum stress sensor, is considered a key component in signal amplification during the viral infection response when activated in conjunction with the RIG-I complex." (PMID 40867782, 2025).
prostate carcinoma (35 papers, 2012 to 2025). A carcinoma that arises from epithelial cells of the prostate gland. "Seven genes (ATM, BCL2, ERN1, FOS, NRAS, PIK3R1, and SP1) were regulated in opposite directions in patients with HD and prostate cancer." (PMID 37298337, 2023). "Previous studies reported that IRAK2 participates in the UPR in the presence of ER stress in prostate cancer cells; therefore, we wondered if IRAK2 could be involved in the ERN1 signalling pathway in BCSCs." (PMID 36768848, 2023).
glioma (34 papers, 2012 to 2025). A benign or malignant brain and spinal cord tumor that arises from glial cells (astrocytes, oligodendrocytes, ependymal cells). "ERN1 was also found to be directly linked to changes in the regulation of the genes belonging to the homeobox complex, which are involved in central nervous system embryology and are known to have a role in the proliferation of glioma cells both in paediatric and adult patients." (PMID 39595047, 2024). "Overall, all these studies point towards a key role of ERN1 in glioma cell proliferation, a role which seems to affect ERN1-dependent genes to a different extent under glutamine deprivation." (PMID 39595047, 2024). "Endoplasmic reticulum-induced stress via tunicamycin in glioma cells, together with the suppression of ERN1, downregulates PRPS1 and PRPS2 gene expression levels." (PMID 35741038, 2022). "Previously, we showed that inhibition of the Unfolded Protein Response (UPR) sensor IRE1α (also named ERN1) down-regulated the expression of several pro-angiogenic growth factors in a glioma model." (PMID 24330607, 2013). "Furthermore, the expression of PRPS1, PRPS2, PRPSAP1 (PAP39) and PRPSAP2 (PAP41) genes in U87 glioma cells is not inhibited by ERN1 (EC 2.7.11, endoribonuclease activity of endoplasmic reticulum to nuclei-1)." (PMID 35741038, 2022).
colorectal cancer (29 papers, 2017 to 2026). A primary or metastatic malignant neoplasm that affects the colon or rectum. "This screen established a relationship between ERN1 and JUN and highlighted the relevance of the ERN1-JNK-JUN pathway as a novel regulator of MEKi response in human KRAS-mutant colorectal cancer, providing a therapeutically exploitable vulnerability." (PMID 35740503, 2022). "In KRAS mutant colorectal cancer cell lines, genetic ablation of the human ortholog of IRE1, ERN1, does not affect growth but sensitizes to MEK inhibition." (PMID 30482246, 2018). "However, as a human homologous gene of IRE1, knockout of ERN1 (endoplasmic reticulum to nucleus signaling 1) in KRAS-mutant colorectal cancer cells does not affect cell growth but does sensitize the cells to MEK inhibition." (PMID 38275900, 2024).
lung carcinoma (29 papers, 2015 to 2025). "The anti-cancer activity of DMC occurs through promoted expression of ER stress-associated proteins HSPA5, DDIT3, ERN1, ATF6A, ATF6B, CASP4 and CAPS12 in human lung cancer NCI-H460 cells." (PMID 36497321, 2022). "BDMC increases ER stress-associated proteins expression such as HSPA5, DDIT3, ERN1, ERN2/IRE-1β, ATF6, ATF6B and CASP4, which results in cell apoptosis in the human lung cancer NCI H460 cell line." (PMID 36497321, 2022).
colon carcinoma (28 papers, 2012 to 2025). "Our genome-wide CRISPR/Cas9 screen identified a series of genetic events that can reinstate MEK inhibitor resistance in ERN1 knockout colon cancer cells." (PMID 30482246, 2018). "We identify the ERN1-JNK-JUN pathway as a novel regulator of MEK inhibitor response in KRAS mutant colon cancer, and point to synthetic lethality of MEK inhibition with therapeutics targeting JUN activating kinases, TAK1 and JNK." (PMID 30482246, 2018). "We identify the ERN1-JNK-JUN pathway as a novel regulator of MEK inhibitor response in KRAS mutant colon cancer." (PMID 30482246, 2018). "Considering unsatisfactory performance of MEK inhibitors in clinical trials, we used ERN1 knockout colon cancer cells as a model to study resistance mechanisms to MEK inhibition." (PMID 30482246, 2018). "Taken together, our findings identify an unexpected role for the Unfolded Protein Response executor ERN1 in determining the response to MEK inhibition in KRAS-driven colon cancer." (PMID 30482246, 2018). "To investigate how ERN1 modulates MEK inhibitor responses, we performed genetic screens in ERN1 knockout KRAS mutant colon cancer cells to identify genes whose inactivation confers resistance to MEK inhibition." (PMID 30482246, 2018). "Finally, we find that ERN1 is an important regulator of JUN activity, which becomes crucial for survival in KRAS mutant colon cancer under conditions of abrogated MAPK signaling." (PMID 30482246, 2018). "To test whether ERN1 is essential in cells with active RAS signaling, we created ERN1 knockout (KO) LoVo, HCT-116, SW480, and DLD1 KRAS mutant colon cancer cells using lentiviral CRISPR-Cas9 vectors." (PMID 30482246, 2018).
colitis (25 papers, 2012 to 2025). Inflammation of the colon. "Ern1 knockout (KO) in mice directly leads to death during the state of embryonic process, while Ern2 KO in mice results in increased ER stress, shortened latency of colitis, exacerbated DSS-induced colitis, induced idiopathic colitis, and aggravated severity of colitis." (PMID 35402506, 2022).
steatosis (20 papers, 2012 to 2025). Increased lipid within the cytoplasm of cells. "Studies indicate that ERN1 activation is associated with hepatocyte steatosis and inflammatory responses, suggesting its potential as a therapeutic target in NAFLD progression." (PMID 41378206, 2025). "Another potential beneficial effect of 2′-FL that may have contributed to the observed decrease in steatosis is the counter regulation of several important factors associated with ER stress such as ATF4, ATF6, ERN1, NUPR1 indicating an overall attenuation of the ER stress response." (PMID 35782914, 2022).
triple-negative breast carcinoma (20 papers, 2015 to 2025). An invasive breast carcinoma which is negative for expression of estrogen receptor (ER), progesterone receptor (PR), and human epidermal growth factor receptor 2 (HER2). "Since XBP1 is a known target of ERN1 and implicated in triple-negative breast cancer, we tested regulation of the gene by qPCR." (PMID 27829216, 2016). "Strietz noted that triple-negative breast cancer cells lacking ALPK1 or ERN1 were less tumorigenic than those not lacking them, suggesting their role in the same pathway." (PMID 36139553, 2022).
pancreatic cancer (19 papers, 2014 to 2025). "Notably, ERN1 silencing reversed the chemo-sensitive phenotype of these two cell lines, providing a molecular link between the MIA2I141M variant and pancreatic cancer cell chemo-response." (PMID 25657029, 2015). "Consistently, pancreatic cancer cell lines expressing the MIA2I141M variant had a higher expression of ERN1 while no such effect was found for the other tested UPR molecules." (PMID 25657029, 2015). "In addition, we demonstrated that pancreatic cancer cells expressed high levels of genes belonging to the ER stress/UPR system including proximal signal sensors (PERK, ATF6 and ERN1), the chaperone lectins (Calnexin) and the folding catalysts (PDI)." (PMID 25657029, 2015).
neuroblastoma (16 papers, 2012 to 2025). Neuroblastoma (NB) is the most common solid, extracranial childhood tumor. "As treatment upregulated expression of ERN1 in a concentration dependent manner in neuroblastoma SH-SY5Y cells, indicating that As-induced ER stress activates the IRE1 UPR pathway." (PMID 32246005, 2020).